FGF2 (fibroblast growth factor 2)
Diseases named in the same sentence as FGF2 in open-access papers (continued):
Sharing a sentence is not in itself a finding about the gene and the disease.
depression (54 papers, 2012 to 2026). "Circulating FGF2 level is linked with depression severity and symptomatology in men and women reinforcing involvement of this growth factor in mood disorders." (PMID 41545369, 2026). "FGF-2 has been implicated in stress-related mood disorders, such as depression, and its expression is reduced in the hippocampus of MDD patients." (PMID 37298063, 2023). "Changes in Fgfr1 expression, and FGF2 levels in the hippocampus are linked to major depression and anxiety, as well as to responses to antidepressants." (PMID 28439461, 2017). "Fibroblast growth factor-2 (FGF-2) is another growth factor associated with depression." (PMID 36986674, 2023). "A recent rat study implicated FGF2 signaling in the antidepressant effects of high-frequency repetitive transcranial magnetic stimulation, attaching additional significance to this pathway in the treatment of depression." (PMID 36081576, 2022). "A recent study measured serum FGF2 levels in the 28 MDD patients before and after treatment and 30 healthy controls using enzyme-linked immunosorbent assay, and found that serum FGF2 levels in patients with depression were significantly lower than those in healthy controls, consistent to our result." (PMID 34667146, 2021). "Diminished neuronal FGF-2 levels are linked to neurological diseases including AD and depression." (PMID 32038161, 2019). "Two lines of evidence demonstrate that FGF2 modulate microglia activation in hippocampus which may underlie the pathogenesis of neuroinflammation-associated depression." (PMID 30135647, 2018). "However, there is no direct evidence to show whether the antidepressant role of FGF2 in neuroinflammation-associated depression involves the actions on microglia in the brain, the present finding is the first answer to this issue." (PMID 30135647, 2018). "Though some studies suggest that FGF2 has potent effect not only on neurons but on glia, whether and how FGF2 affect microglia in neuroinflammation-associated depression remains elucidative." (PMID 30135647, 2018). "We report that environmental enrichment dampens stress-induced loss of endothelial tight junction Claudin-5 (Cldn5) along with anxiety- and depression-like behaviors in male mice via an increase in fibroblast growth factor 2 (Fgf2)." (PMID 41545369, 2026). "In humans, FGF-2 reactivity predicted anxiety, depression, and stress over the course of the COVID-19 pandemic." (PMID 39595087, 2024). "When looking at fgf2 expression in brain regions of individuals with depression, schizophrenia or bipolar disorder, the results are interesting." (PMID 35599764, 2022). "The density of fgf2 mRNA positive cells in CA4 was in depression compared to controls, but overall the fgf2 mRNA levels were higher in DG than compared to the CA1 and CA4 regions of the brain." (PMID 35599764, 2022). "Fibroblast growth factors are associated with skeletal muscle development, and a study has found that fibroblast growth factor-2 can affect depression." (PMID 36520780, 2022). "Other neurotrophic/growth factors linked to depression include the vascular endothelial growth factor (VEGF), the fibroblast growth factor 2 (FGF2), and the insulin-like growth factor 1 (IGF-1)." (PMID 35056845, 2022). "The following are promising salivary biomarkers of stress, anxiety or depression: cortisol, immunoglobulin A (sIgA), lysozyme, melatonin, α-amylase (sAA), chromogranin A (CgA) and fibroblast growth factor 2 (FGF-2)." (PMID 33535653, 2021). "There is growing evidence that the expression of the FGF2 gene is down-regulated in the brain region of depressed patients and plays an antidepressant role in animal models of depression." (PMID 34667146, 2021). "Currently, among the twenty-two identified FGFs, FGF2, FGF9, FGF21, and FGF22 have been found to be associated with depression." (PMID 30804785, 2019). "FGF2-ERK signaling pathway was also reported to be involved in the neuroinflammation induced model of depression." (PMID 30804785, 2019).
depression (continued). "FGF-2 is known to be sensitive to stress exposure, and postmortem analyses of brains from patients with major depressive disorder (MDD) revealed significant reductions in FGF-2 mRNA levels in the hippocampus." (PMID 30369869, 2018). "To further investigate the potential of FGF-2 as a therapeutic target for depression, we explored the antidepressant effects of peripheral FGF-2 on a chronic unpredictable mild stress (CUMS) model." (PMID 30369869, 2018). "In this study, we investigated the antidepressant effects of HMW and LMW FGF-2 on depression induced by chronic stress." (PMID 30369869, 2018). "There are several additional growth factors that also have been implicated in neurogenesis, depression, and treatment response, such as insulin-like growth factor-1 (IGF-1), vascular endothelial growth factor (VEGF), and fibroblast growth factor-2 (FGF-2)." (PMID 25477997, 2014). "Furthermore, central injection of FGF2 reduces proinflammatory responses in the hippocampus in a rat model of depression." (PMID 40538537, 2025). "FGF-2 levels were associated with decreased depression-like behaviors in chronic unpredictable stress in mice and FGF-2 administration showed antidepressant-like effects, reducing depression-like behaviors in rodent models." (PMID 39595087, 2024). "Indeed, we showed here that the expression of neurotrophic factors, such as BDNF, NGF, and FGF-2, which are negatively affected in the pathogenesis of depressive disorders, can be enhanced by short-term treatment with irisin." (PMID 37298063, 2023). "In the literature, you can find publications indicating the relationship between stress, depression and/or anxiety and the concentration of cortisol, immunoglobulin A, lysozyme, melatonin, alpha-amylase, chromogranin A and/or fibroblast growth factor 2 in saliva." (PMID 33535653, 2021). "Direct relationships were suggested when the intracerebroventricular injection of FGF2 resulted in antidepressant effects, which were also observed after FGF2 infusion into the prefrontal cortex in chronic unpredictable stress models of depression." (PMID 33860438, 2021). "Together with BDNF, FGF-2 is a second important growth factor marker in depression." (PMID 33255237, 2020). "By activating ERK/MAPK pathway, FGF2 could also increase the expression of glucocorticoid receptor and might reduce the likelihood of depression." (PMID 30804785, 2019). "There were discrepant results of clinical studies on the relationship between FGF2 and depression." (PMID 30804785, 2019). "We hypothesize that the antidepressant effects of FGF2 and the neuroinflammation-induced depression may involve the modulation of microglia changed by FGF2 and FGFR inhibitor." (PMID 30135647, 2018). "To determine whether AKT and ERK activation are involved in the effect of FGF-2 on depression, we first determined the levels of p-AKT and p-ERK in the hippocampus." (PMID 30369869, 2018). "In addition, the central administration of FGF-2 improved depression-like behaviors in several animal models of depression." (PMID 30369869, 2018). "However, to date no published study have reported the association between FGF20 gene and depression; although some studies have reported association between another FGF system transcripts, such as FGF2, FGF12 and FGFR2 with major depressive disorder." (PMID 30241547, 2018). "However, most of these studies examined the role of central LMW FGF-2 in animal models of depression, which limits the potential of FGF-2 for depression in clinical use." (PMID 30369869, 2018). "In general, treatment with HMW or LMW FGF-2 injection ameliorated the depression-like behaviors." (PMID 30369869, 2018). "Further investigation of different FGF-2 isoforms may reveal new research targets and therapeutic strategies for the prevention and treatment of depression." (PMID 30369869, 2018). "Furthermore, FGF2 and FGFR1 signaling in the prefrontal cortex is implicated in human depression and in rodent models of depression." (PMID 28674667, 2017).
depression (continued). "In depression, neuromodulation of neuronal networks in the raphe-hippocampal system and the cortical regions via 5-HT and fibroblast growth factor 2 involves either FGFR1-5-HT1A heteroreceptor complexes or the 5-HT isoreceptor complexes such as 5-HT1A-5-HT7 and 5-HT1A-5-HT2A." (PMID 28270751, 2017). "It is hypothesized that Fgf2 and Fgfr1 are downregulated in depression and anxiety, and this downregulation can be partially reversed by antidepressant treatment (Turner, Watson & Akil, 2012b; Turner, Watson & Akil, 2012a)." (PMID 28439461, 2017). "Furthermore, intracerebroventricular administration of FGF-2 produces antidepressant-like effects in different types of animal models of depression." (PMID 23227251, 2012). "Several lines of evidence have demonstrated the relevance of FGF-2 to depression." (PMID 23227251, 2012). "Furthermore, fibroblast growth factor-2 (FGF2) promotes proliferation of neural progenitor cells, enhances synaptic plasticity and axonal branching, and ameliorates cognitive deficit in neurodegenerative diseases and depression." (PMID 35562946, 2022). "Results obtained from these salivary biomarkers offer insight into individuals’ stress levels, anxiety or depression, primarily using salivary cortisol, immunoglobulin A (sIgA), salivary alpha-amylase, chromogranin A, lysozyme, melatonin, and fibroblast growth factor 2 (FGF-2)." (PMID 36285968, 2022). "Molecular and behavioral studies deepened the role of neurotrophic/growth factors (such as BDNF, NGF, IGF-1, and FGF-2) in depression, demonstrating that the levels of those factors were reduced in animal models and in depressed and/or stressed patients (“neurotrophic hypothesis of depression”)." (PMID 35886944, 2022). "Moreover, pretreatment of FGF2 elevated neuroligin 1 expression and trafficking of GluR1/2 into the postsynaptic compartment of mice exposed to prenatal corticosterone, improving spatial memory and depression/anxiety-like behaviors." (PMID 35562616, 2022). "In addition to BDNF, also IGF-1, FGF-2, and NGF have been implicated in depressive disorders." (PMID 35886944, 2022). "Notably, FGF2 may have indirectly enhanced neuronal activity by the stimulation of astrocyte proliferation, which is reduced in rodent depression models." (PMID 33860438, 2021). "Hence the role of FGF2 and related networks in depression are well documented in the brain." (PMID 34667146, 2021). "Whether astroglia, astroglial functions, or HPA changes are the downstream target of FGF2 mediated changes induced by fluoxetine remains to be determined, however, the current study reaffirms the potential of FGF2 as a novel therapeutic target in the treatment of depression and anxiety disorders." (PMID 30273396, 2018). "Interestingly, the present data showed that FGF2 not only ameliorated the increased production of pro-inflammatory cytokines in the neuroinflammation induced model of depression, but also enhanced the level of IL-10, a representative anti-inflammatory cytokine." (PMID 30135647, 2018). "Interestingly, FGF-2 has received considerable attention for its role in depression." (PMID 28323284, 2017). "Furthermore, blockade of FGF-2 receptor signaling or genetic knockout of FGF-2 antagonized the behavioral effects of antidepressants in rodent models of depression, suggesting that this growth factor may be necessary for antidepressant effects to occur." (PMID 23675319, 2013). "Therefore, to elucidate how antidepressants induce the secretion of FGF2 from astrocytes may lead to the further understanding the action mechanisms of antidepressants and the development of a new therapeutic target of major depression." (PMID 24260208, 2013). "In addition, antidepressant efficacy is blocked in FGF-2 deficient mice in the tail suspension test, and blocked by treatment with a FGF receptors (FGFR) inhibitor in the chronic unpredictable stress model of depression." (PMID 23227251, 2012).
depression (continued). "Therefore, in a group of mice already submitted to a behavioral test of depression, we examined the expression of some neurotrophic/growth factors associated with the pathogenesis of depressive disorders, such as BDNF, IGF-1, nerve growth factor (NGF), and fibroblast growth factor 2 (FGF-2)." (PMID 37298063, 2023). "There are several growth factors, including brain-derived neurotrophic factors (BDNFs), vascular endothelial growth factors (VEGFs), fibroblast growth factors 2 (FGF-2), and insulin growth factor 1 (IGF1) that are involved in depression." (PMID 36362315, 2022). "Here, we mainly concentrated on the reported depression-related FGF system members, including FGFR1, FGF2, FGF9, FGF21, and FGF22." (PMID 30804785, 2019). "It is well to be reminded that, FGF2 and FGF9 were found to have the opposite effect through chronic administration of FGFs, that is, FGF2 reduced anxiety- and depression-like behaviors, while FGF9 increased anxiety- and depression-like behaviors." (PMID 30804785, 2019). "Our previous work has demonstrated that exogenous fibroblast growth factor 2 (FGF2) reverses the depressive-like behaviors and the impaired hippocampal neurogenesis in a neuroinflammatory model of depression." (PMID 30135647, 2018). "It therefore became of interest to study the FGF2 and 5-HT1A agonist regulation of the FGFR1-5-HT1A heterocomplexes in the hippocampus and dorsal raphe in a genetic rat model of depression (FSL) vs. the control SD strain using the in situ PLA." (PMID 29066953, 2017). "Secondary outcomes include serum biomarkers of SCI osteoporosis (sclerostin, P1NP and β-CTX), markers of immune function (IL-6, IL-10, FGF2, INF-γ, TNF-α), neurological function, body composition, depression and quality of life." (PMID 25563584, 2015). "The data regarding NGF involvement in depression have been more sparse than those involving BDNF and FGF-2." (PMID 23675319, 2013). "It has been reported that Saponin D can downregulate the expression of NF-κB in rat hippocampal neurons and improve the depression-like behavior induced by chronic unpredictable mild stress (CUMS) by downregulating Mir-155 expression and upregulating fibroblast growth factor 2 (FGF2) expression." (PMID 36408279, 2022). "A potential role for the FGF system in depression and antidepressant action was indicated by microarray gene expression analysis of postmortem frontal cortex brain tissue from major depressive disorder (MDD) patients, showing dysregulation of multiple FGF transcripts and a reduction in FGF2." (PMID 36081576, 2022). "Pending on large sample validation, FGF2, and related pathway may become a potential molecular targets to an exploration of the pathogenesis of MDD, and provide new ideas for the diagnosis and treatment of depression in the future." (PMID 34667146, 2021). "Further studies are needed to investigate whether and how FGF2 inhibitor SU5402 can prevent the antidepressant effect of FGF2 and provide more experimental evidence for the relevance of FGF2/FGFR pathway in inflammation-induced depression." (PMID 30135647, 2018).
depression (continued). "Therefore, studying whether FGF-2 affects the expression and activity of BDNF as an indicator of depression would be interesting." (PMID 30369869, 2018). "Unlike BDNF, NGF, and FGF-2, which were reduced in association with depression, plasma levels of VEGF were elevated or unchanged in drug-free patients with an acute episode of major depression and VEGF levels were unrelated to depression scores." (PMID 23675319, 2013). "Similarly, slow infusion of FGF2 showed antidepressant effects in chronic unpredictable stress (CUS) rats, and the treatment of antidepressants failed to improve depression-like behaviors after the administration of FGFR inhibitors." (PMID 30804785, 2019).